THY1 (Thy-1 cell surface antigen)
Diseases named in the same sentence as THY1 in open-access papers (continued):
Sharing a sentence is not in itself a finding about the gene and the disease.
cancer (continued). "Thy-1 (CD90) has been shown to be a potential marker for several different types of cancer." (PMID 27332878, 2016). "Evidence is emerging to support the concept that these cells are epigenetically reprogramed so that a group of antifibrotic genes, including COX-2, Thy-1, and IP-10, are epigenetically silenced in a way similar to the epigenetic silencing of tumor suppressor genes in cancers." (PMID 24652950, 2014). "The CD90 (Thy-1) had been proposed as one of the important molecules in cancer, including in HCC." (PMID 24116172, 2013). "Finally, the percentage of myoepithelial cells that stained brightly with phalloidin, as well as Thy-1 expression were decreased in the RMECs from carcinomas as compared to those of the mammary gland of untreated control rats (data not shown)." (PMID 22022542, 2011). "However, over-expression of THY1 also favored a better prognosis in some cancers." (PMID 38819947, 2024). "However, depending on the cancer type, THY-1 might have ambivalent properties regarding its anti- or protumoral activities." (PMID 37628927, 2023). "Studying the effects of the Thy-1/integrin/Syndecan-4 trimolecular complex in the context of mechanotransduction is important since mechanical strain controls many physiological and pathological functions, such as embryonic development, morphogenesis, wound healing, cancer, and atherosclerosis." (PMID 38099295, 2023). "The combined use of Bcl11b and Thy1 confirmed the existence of cellular intermediates sharing transcriptomic but also epigenomic traits, therefore providing a concrete demonstration of the previously proposed correlative analogies between cancer and reprogramming." (PMID 36075976, 2022). "However, most cancers showed THY1 and COL1A1 hypomethylation compared to normal samples." (PMID 36032075, 2022). "Therefore, an interesting possibility is that, apart from aligning the ECM protein fibronectin, these Thy-1+/+ CAFs could guide integrin-positive cancer cells to migrate and metastasize." (PMID 35733855, 2022). "However, the importance of THY1 expression in human cancers is controversial." (PMID 35172861, 2022). "In this context, Thymus cell antigen 1 (THY1), also called Cluster of Differentiation 90 (CD90), is a 25–37 KD glycophosphatidylinositol (GPI)-anchored protein expressed in numerous cell types, including T cells, neurons, endothelial cells, and cancer-associated fibroblasts (CAFs)." (PMID 35172861, 2022). "Furthermore, THY1 levels also positively correlated with cancer stemness." (PMID 35071018, 2021). "Interestingly, ASPN and THY1 have both been shown to impact cancer stem cells." (PMID 33600062, 2021). "To assess the clinical relevance of COL1A1, ITGB1, THY1, and PDGFRA genes in UCEC progression, we examined the correlation between their transcriptional expression levels and cancer stages." (PMID 40817072, 2025). "When COL1A1, ITGB1, THY1, and PDGFRA are down-regulated, they contribute to a cascade of molecular events that profoundly impact cancer development and progression." (PMID 40817072, 2025). "In summary, our investigation into the role of immune-related genes, including COL1A1, ITGB1, THY1, and PDGFRA, in UCEC sheds light on their multifaceted contributions to cancer development and progression." (PMID 40817072, 2025). "Similar to the cancer tissue samples, a significant weak positive correlation was also seen between MMP2 and PDPN and between THY1 and PDPN in adjacent normal tissues." (PMID 39335130, 2024). "Intriguingly, we also found that the cancer stem cells (CSC) score, calculated using common CSC markers (EPCAM, CD24, KRT19, SOX9, PROM1, CD44, THY1, CD47), was significantly higher in the EMT-subtype." (PMID 39095854, 2024). "Those cancers with high expression of PDPN, MMP2 and THY1 were enriched for immune-mediated pathways, such as inflammatory response, IFN response, and IL6-JAK-STAT signaling." (PMID 39335130, 2024).
cancer (continued). "This was achieved by suppressing cancer cell markers CD133, Thy1, and napsin, as presented in NOD/SCID mice." (PMID 36672696, 2023). "Yet to our knowledge, no study has been conducted to investigate the interaction between THY1 and SRC in NPC cancer development or the functional relevance of their interaction." (PMID 37046850, 2023). "The strong downregulation of Thy-1 in B9T-OC can also be seen as a trait opposite to a malignant phenotype, as Thy-1 is often used as a biomarker of several tumors, including HCC and cancer stem cells." (PMID 35159174, 2022). "The obtained results showed that tumors from LPC pIL-17 have a significant increase in cancer cell and CSC markers (Cd133, Klf4, Thy1, Ck19, Afp and Gpc3) when compared to tumors from LPC pEmpty." (PMID 35342340, 2022). "Fibroblasts were isolated by removing immune (anti-CD45) and cancer cells (anti-CD90.1/Thy1.1) and then selecting for cells expressing CAF marker Thy1 (CD90.2/Thy1.2)." (PMID 32455670, 2020). "High expression of the putative cancer and hematopoietic stem cell marker THY1/CD90 and WNT11 and CTNNB1 also suggest potential novel therapeutic strategies to increase pCR rates." (PMID 30967156, 2019). "For example, Thy-1/CD90 plays an important role as a β3 integrin ligand in fibroblasts and cancer cells." (PMID 31428610, 2019). "We screened for cancer cells expressing at least one EMT marker, such as ACTA2, EPCAM, CD44, THY1, VIM, FN1, ZEB1 or CDH1." (PMID 29079795, 2017). "The six selected genes (TWIST1, LAMB1, THY1, EZH2, SALL4, and TCF3) are involved in cell differentiation, HCC cancer stem cells (CSCs) markers, and CSCs involved pathways." (PMID 28158312, 2017). "The other genes (MT-1G and THY1) which were found to be hypomethylated in this study have not been previously investigated in SSc and SLE, though are known to be hypermethylated in cancer." (PMID 25986394, 2015). "Correspondingly, THY-1 cell surface antigen (CD90), tissue inhibitor of metalloproteinase (TIMP)-4 and SERPIN F1, previously reported to negatively regulate invasion of cancer cells, were found to be downregulated." (PMID 25682871, 2015). "Subsequent enrichment in Sca-1 positive cancer stem cells was shown for mouse mammary tumor models, such as mouse mammary tumor virus (MMTV)-Her2/neu and MMTV-Wnt1, and Thy1/CD24 expression further defined cancer stem cells in the Wnt1 model." (PMID 18241344, 2008). "It has been reported that Thy1 induces ATP release and activates P2X7 receptor via the integrin αvβ3 leading to calcium entry, which is required for focal adhesion formation, migration and invasion of astrocytes and cancer cells." (PMID 41557138, 2026). "A previous study reported that Thy1 induces ATP release and activates P2X7 receptor via the integrin αvβ3 leading to calcium entry, which is required for focal adhesion formation, migration and invasion of astrocytes and cancer cells." (PMID 41557138, 2026). "This is promising for planning further clinical development of the Thy-1-targeted contrast agent MB for the early and accurate diagnosis of human PDAC using molecular imaging, thus improving the overall survival of patients with this fatal cancer." (PMID 36747131, 2023). "Thus, we aimed to trace cancer markers such as CD133, Thy1, and napsin in solid tumor tissues using immunostaining and counted them using an ImageJ programmed system (N = 4)." (PMID 36672696, 2023). "CC-3 represented the mesenchymal-like cancer cell subpopulation that expressed mesenchymal genes such as Prrx1, Col6a1, Thy1, and Vim, but not epithelial marker genes such as Epcam and Cdh1." (PMID 37190324, 2023). "Moreover, class II tumors show elevated expression of KRT20, which is highly linked to differentiated umbrella cells or CIS lesions, and ALDH1A1, ADH1A2, PROM1 (CD133), NES, and THY1 (CD90), which are cancer stem cell markers." (PMID 37525073, 2023).
cancer (continued). "In further studies, CAFs cell populations have been discovered that they can be separated using PDGFRα/β and Thy-1 cell surface antigen (CD90), with GPR77 and CD10 as unique CAFs cell markers being able to maintain cancer cell stemness when promoting chemoresistance." (PMID 36439106, 2022). "Moreover, THY1 expression was positively related to the level of SOX9, a classical biomarker of cancer stemness." (PMID 35071018, 2021). "and observed that THY1 was highly expressed in the wound-healing subtype (C1) and TGF-βdominant subtype (C6), which means that THY1 is an immunosuppressive participant in malignant tumors." (PMID 35071018, 2021). "Patients in PD group had the highest expression of THY1 and SOX9, a marker of cancer stemness." (PMID 35071018, 2021). "For example, ADT levels of EPCAM on cancer/epithelial cells (c0, c4, c8, c14 and c15), CD31 (PECAM1) and CD34 on endothelial cells (c7 and c9), CD146 (MCAM) on perivascular cells (c11), CD90 (THY1) and CD34 on CAFs (c13) and CD45 (PTPRC) on immune cells (c3, c5 and c12)." (PMID 33971952, 2021). "CD90, also known as THY-1, is a GPI-anchored adhesion protein of the immunoglobulin superfamily, which is another widespread mesenchymal marker related to poor prognosis in many cancers." (PMID 33260962, 2020). "Therefore, we probed the proteomic data for expression pattern of other well-known cancer stem cell markers such as ALDH1A1 (2.6 fold), CD151 (2.1 fold), CD47 (1.9 fold) and THY1 (3.5 fold)." (PMID 31438645, 2019). "The relevance of THY-1 (CD90) for cellular adhesion capacity was highlighted for CD90 negative carcinoma, which compared to their CD90 positive counterparts lack the ability to form spheres." (PMID 31405163, 2019). "Additionally, chemo-resistant tumors have already shown high expression of THY1 in other types of cancer, although there is no description in IGC." (PMID 38254918, 2023). "However, the biological mechanisms of the interactions between TNXB-SDC4, THY1-(ITGAX+ITGB2), ICAM1-(ITGAX+ITGB2), and C3-(ITGAX+ITGB2) ligand-receptor pairs in cancer remain unclear and warrant further investigation." (PMID 37954130, 2023). "In order to validate the hypothesis that THY1 is related to cancer stemness and immunotherapy resistance, we performed IHC staining on six tissue samples of LUAD patients who received at least three cycles of PD-1 mAb treatments using THY1 and SOX9 antibodies." (PMID 35071018, 2021). "Also, mRNA expression of the cancer stem cell (CSC) markers CD90 (Thy1) and CD133 (Prom1) was not substantially different between wt and Casp2−/− liver tumors (Fig EV2C)." (PMID 33225610, 2020). "In addition to the commonly known hypomethylated genes in SLE and SSc, there are other hypomethylated genes (such as MT-1G and THY-1) that have not previously been investigated in SLE and SSc though are known to be hypermethylated in cancer." (PMID 25986394, 2015). "Finally, we depleted Thy1 and MFGE8 from CAFs and we tested whether tracks lacking these two proteins could still orient cancer cell migration." (PMID 37585527, 2023).
infection (49 papers, 2008 to 2026). The state of being infected such as from the introduction of a foreign agent such as serum, vaccine, antigenic substance or organism. "Similar blocking result with THY-1 antibody was also seen when infectivity was assayed at 3 days post-infection by virus-encoded GFP (P = 0.0004, 3 independent experiments)." (PMID 26147640, 2015). "Compared to the uninfected group, the proportion of C4 (Thy1+NK) cells within the total NK cells increased at week four post-infection and decreased at week six post-infection." (PMID 40244063, 2025). "The cytotoxic function of the Thy1+NK cells was active at four weeks post-infection and was inhibited at six weeks post-infection." (PMID 40244063, 2025). "C3 (Cx3cr1+NK) and C4 (Thy1+NK) increased at week four post-infection, and other subsets decreased continuously." (PMID 40244063, 2025). "In our study, we observed that the proportion of C4 NK cells (Thy1+NK) increased significantly in the hepatic NK cells at four weeks post-infection and decreased at six weeks post-infection." (PMID 40244063, 2025). "Thy1(C4 marker) expression increased significantly at week four and decreased at week six post-infection." (PMID 40244063, 2025). "The result indicated that Thy1+ NK cell cytotoxicity increased four weeks post-infection but was attenuated six weeks post-infection." (PMID 40244063, 2025). "To further understand the role of ILCs in bladder defense, we performed RNA-seq on bladder samples taken from Rag2−/− mice treated with isotype control or anti-Thy-1 antibody at 24 h following infection." (PMID 35845169, 2022). "To further explore if ILC1s were sufficient and necessary for maintaining DCs during infection, we next tested the effects of selective depletion of Thy1+ cells in WT and Rag2-/- mice." (PMID 33465134, 2021). "Because only 7.2% of cultured FBs were infected when the CM Adv vector dose (10 MOI) was used, we had to increase the dose for THY1+ FBs by 10 times to reach an infection efficiency >95%." (PMID 34646377, 2021). "THY-1 is known to interact with several host cell proteins important for infection and is expressed on numerous types of cells that can be infected by HCMV." (PMID 26147640, 2015). "Direct ex vivo analysis of splenocytes by flow cytometry on day 9 post-infection (p.i.)revealed a small Ifng/Thy1." (PMID 26646149, 2015). "Both viral-mediated infection of GABAergic neurons in the SNr and the Thy1-ChR2 transgenic mouse line exhibited cell-type specific expression of ChR2 in GABAergic neurons of the SN, but not in dopamine neurons." (PMID 24849626, 2014). "Improved (although not significant) Thy1 repression continued to 7 days in MEF expressing OSK and treated with 100 nM pTAT-mcMyc protein, with Thy1 repression maintained to 12 days after infection." (PMID 22619682, 2012). "At 14 days, pretreatment of MEF with exogenous Klf4 + 100 nM pTAT-mcMyc before Oct4/Sox2 infection at day 0, significantly repressed Thy1 than cells infected with Oct4/Sox2 alone." (PMID 22619682, 2012). "FACS analysis for Thy1+ cells was performed on days 0, 7, and 14 after mOct4/mSox2 infection with percentage Thy1+ cells in each treatment group normalized to untreated control MEF." (PMID 22619682, 2012). "The representation of this KLRG1hi population rose from approximately 5% to a peak of 20–25% of the liver Thy1+ NK cell population by days 4–7 after infection, and then contracted to baseline levels by 21 days after challenge." (PMID 21829360, 2011). "We demonstrate that immune protection against infection from a lethal dose of virus can be adoptively transferred with memory hepatic Thy1+ NK cells that were primed with live virus." (PMID 21829360, 2011). "Similarly, infection with tetO-YAP lentiviruses of neurons from mice bearing Syn1-Cre or Thy1-Cre and the R26-LSL-rtTA-IRES-EGFP reporter generated EGFP-positive yNSCs." (PMID 27641305, 2016). "In summary, memory T cells in this infection show poor maintenance of Ifng/Thy1." (PMID 26646149, 2015).
infection (continued). "Interestingly, preinfection with Klf4 (thus prerepressing Thy1), with subsequent Oct4/Sox2 infection, was equally effective at repressing Thy1 at 14 days than infecting cells concurrently with OSK (compare blue and orange lines)." (PMID 22619682, 2012). "However, addition of 100 nM pTAT-mcMyc protein to OSK provirus-expressing MEF further promotes Thy1 suppression to 7 days after infection, an improvement approaching statistical significance on OSK alone (P = 0.07)." (PMID 22619682, 2012). "A gradual downregulation of Thy1 was observed in OSK expressing cells over 12 days post infection." (PMID 22619682, 2012). "After 5 days of Klf4 expression ± recombinant protein treatment (designated day 0), treatment groups and untreated MEFs were (i) collected and analysed by FACS for proportion of Thy1+ cells and (ii) replated for a second infection of retrovirus for mOct4 and mSox2." (PMID 22619682, 2012). "The naïve T- and Thy1-depleted mice also succumbed to infection." (PMID 21829360, 2011). "We wanted to determine whether the expansion of Thy1+ NK cells observed in the liver and spleen during primary infection were a consequence of proliferation or an alteration in NK cell trafficking." (PMID 21829360, 2011). "Of the naive RAG1ko mice that received 1×105 primed Thy1+ liver NK cells, 41% (9/22) were able to resolve a systemic, lethal vaccinia virus challenge infection, while only 2% (1/49) of RAG1ko mice that received other purified NK cell subpopulations were able to resolve and survive infection." (PMID 21829360, 2011). "We further sought to define a durable cell surface marker expression profile acquired after a primary infection that might identify a memory cell subpopulation within the liver-resident Thy1+ NK cell compartment." (PMID 21829360, 2011). "Interestingly, the Thy-1 cellular protein, known to play an important role to facilitate hCMV entry into cells via macropinocytosis, was significantly enriched in sEVs upon infection." (PMID 36146834, 2022). "We identified ten NK subgroup-specific marker molecules (Kcnj8, Cmah, Ccnd2, Cx3cr1, Thy1, Tnfrsf9, Zbtb20, Gng11, CD226, Egr3) from C0 to C9 and assessed their expression changes during infection using RT-qPCR." (PMID 40244063, 2025). "The infection with LV-sh-YY1 contributed to improved lung pathological manifestations in the bleomycin model mice, while LV-sh-THY1 treatment worsened the lung pathological manifestations, which were alleviated by LV-sh-YY1 (P < 0.05)." (PMID 32396525, 2020). "The physical interactions between HDF/DCs via surface molecules such as Thy-1/Mac-1 (CD11a-CD18) or ICAM-1/LFA-1 (CD11b-CD18) induce activation of both HDF and DCs, promoting the secretion of type I interferons previous to the infection." (PMID 33193307, 2020). "Compared with the control protein at each dose, soluble THY-1 protein reduced HCMV infectivity in a dose-dependent manner in adenocarcinoma cells, and inhibited infection in MRC-5 fibroblasts." (PMID 26147640, 2015). "On day 6 post-infection, Socs4R108X/R108X (Thy1.2) CD8 T cells migrating to the lungs had significantly lower levels of CD69 expression than wild-type (Thy1.1) CD8 cells." (PMID 24809749, 2014). "Experimental results outlined here suggest mcMyc regulates the initial (<5 days) suppression of Thy1 in MEF, followed by a cooperative mechanism driven by mcMyc/Klf4 from 5–9 days after infection." (PMID 22619682, 2012). "This analysis also highlighted a central role for inflammation and infection, evidenced by networks containing genes such as CD74, S100A9, and THY1." (PMID 19513121, 2009). "Knock-down of THY-1 expression with specific siRNAs blocked HCMV-induced phosphorylation of Akt at 15 min post-infection and reduced HCMV infectivity within the first 60 min of infection compared with control siRNAs (p = 0.01, 6 independent experiments)." (PMID 26147640, 2015).